ATF3 (activating transcription factor 3)
Diseases named in the same sentence as ATF3 in open-access papers (continued):
Sharing a sentence is not in itself a finding about the gene and the disease.
tumor (continued). "Univariate analysis identified eight prognostic factors: tumor size, histological grade, serosal invasion, peritoneal dissemination, tumor invasion depth, lymph node metastasis, TNM stage and ATF3 expression." (PMID 34728784, 2021). "In PF-A tumor slides, analysis of top signature genes demonstrated mutually exclusive expression of PF-Ependymal-like (CD36) and PF-NSC-like (ATF3) markers, and some extent of spatial clustering of cells expressing the corresponding programs." (PMID 32663469, 2020). "Extracellular adenosine functions as a ligand that binds to adenosine receptors, such as the ADORA2A, promoting tumor growth by recruitment of MDSCs and ADORA1 that signals downstream of cAMP/PKA/CREB/ATF3/PD-L1." (PMID 32516941, 2020). "Alongside, Gsta1 and Atf3 were upregulated in HCC mice, which have been proposed as potential tumor suppressors in HCC development." (PMID 32559205, 2020). "IHC was used to validate the abundance of IFI6, ATF3 and NOX4 in tumor tissues derived from xenograft model." (PMID 32727517, 2020). "Collectively, our results suggest that the expression of ATF3 and JDP2 in stromal cells, and specifically fibroblasts, can regulate tumor growth." (PMID 30670778, 2019). "Collectively, our results suggest that ATF3 and JDP2 regulate the expression of essential tumor promoting factors expressed by fibroblasts within the tumor microenvironment, and thus restrain tumor growth." (PMID 30670778, 2019). "In our experimental model, we found that tumor growth was significantly higher in the dKO mice than WT mice, indicating that ATF3 and JDP2 expression by host cells contribute to the primary tumor fate." (PMID 30670778, 2019). "The overexpression of TLR4 in SCC13 tumor cells was followed by phosphorylation of ERK1/2 and JNK and increased expression of ATF3." (PMID 28982115, 2017). "This drug has the ability to influence different routes of tumor induction mediated by metabolic stresses (ISR), ATF3 expression, and CHOP, which regulates apoptosis of HNSCC cells." (PMID 26098683, 2015). "The presence of ATF3 and MMP2 proteins was mainly manifested as brown particles in the tumor cytoplasm and marginally in the nuclei." (PMID 25872784, 2015). "This suggests that TTP and ATF3 together harness TLR-mediated inflammation, and future studies should include tests of their functional relationship and how this relates to tumor development and progression." (PMID 25541715, 2014). "Consistent with the effect of ATF3 expression on the growth and invasion of ESCC cells in vitro, ATF3 over-expression significantly inhibited tumor growth." (PMID 25149542, 2014). "Five tumor suppressors or suppressor candidates including NRIP3, CYLD, CD9, ATF3 and OXTR were strongly induced by TSA alone." (PMID 18301774, 2008). "Furthermore, ATF3, as a tumor suppressor gene, is underexpressed in ESCC tissues and negatively correlates with tumor cell proliferation, migration, and invasion." (PMID 40115255, 2025). "The differences between APK and AacinarPK mice supports ATF3 roles in non-epithelial cells of PDAC tumours." (PMID 41198649, 2025). "Expression of ATF3 in epithelial cells appears to maintain early stages of PDAC progression and we and others previously showed ATF3 is expressed in epithelial, fibroblast, and immune cells of established tumours." (PMID 41198649, 2025). "By contrast, consistent with a lack of drug stress, progressive disease tumours fail to induce ATF3 and exhibit even further increased ISGs." (PMID 41249572, 2025). "Additionally, vinburnine activates the P38/MAPK/ATF3 signaling axis, which drives the secretion of interleukin-24 (IL-24), enhancing the functionality of CD8+ T cells and modulating the tumor immune microenvironment to favor antitumor immunity." (PMID 40866941, 2025).
tumor (continued). "Furthermore, the Spearman rank correlation analysis showed a positive correlation between DDIT3 and ATF3 levels in LUSC and LUAD tumor tissues." (PMID 38244586, 2024). "Therefore, inactivating ATF3 can increase CH25H levels, activate CD8+ T cells, and inhibit tumor growth." (PMID 39802954, 2024). "Given the significant increase in ATF3 expression in response to FADS1 inhibition, we set out to further investigate the potential role of ATF3 in mediating the impact of FADS1 inhibition on tumor cell growth." (PMID 38586033, 2024). "Consistently, ROC curves showed that the AUC value of ATF3 was 0.7921 (p < 0.001), suggesting ATF3 could be used to distinguish between HCC tumour and normal tissues." (PMID 37877357, 2023). "ATF3, a transcription factor belongs to the ATF/CREB family, serves as a tumor suppressor in many tumors by inhibiting tumorigenesis, epithelial–mesenchymal transition, and tumor cell invasion and migration." (PMID 37580343, 2023). "Moreover, we examined the expression of ATF3 in the HCC cohort based on the TCGA database (n = 369) and ATF3 was significantly downregulated in tumour tissues compared with adjacent tissues." (PMID 37877357, 2023). "Additionally, we verified the correlation between ATF3 and PD-1 in ESCC using a xenograft tumor model." (PMID 37723150, 2023). "Finally, KO of autophagy-related genes enhanced cell death in the presence of IFN-γ (ATG2A, ATG5, ATF3, and ATF16L1), consistent with autophagy mediating cancer cell resistance to anti-tumor T cells." (PMID 36669486, 2023). "This study demonstrates that the Wnt/β-catenin signaling pathway induces the expression of the transcriptional repressor ATF3, resulting in decreased CCl4 gene expression and ultimately the defective recruitment of CD103+ dendritic cells in the tumor microenvironment." (PMID 35965575, 2022). "Previous studies have demonstrated that transcriptional and post‐transcriptional suppression of SLC7A11 by transcription factors (such as ATF3 and ATF4), H2A deubiquitinases (such as BAP1), and epigenetic modifications (such as H2Bub1) can promote erastin‐induced tumour cell ferroptosis." (PMID 35522946, 2022). "We found that mice lacking ATF3 in DCs exhibited a decreased pulmonary tumor burden as manifested by macroscopic observations, and quantification of lung weight and tumor lesions." (PMID 36333297, 2022). "Moreover, our data uncovered specific regional upregulation of ATF3 in HGSOC patient tissue following NACT exposure, warranting further exploration into how this unique expression pattern correlates to tumor heterogeneity in chemotherapy response." (PMID 36131935, 2022). "Consistent with the lack of alteration in pain behaviors, we did not detect increased macrophage density or ATF-3 expression in the DRG of tumor-bearing mice, which contrasts with the changes seen following induction of CIPN or traumatic nerve injury." (PMID 35962398, 2022). "ATF3 levels were substantially lower in patients with HCC than in healthy individuals of subgroups analyzed based on gender, age, ethnicity, disease stage, tumor grade, weight, and nodal metastasis." (PMID 33407456, 2021). "As a transcription factor, ATF3 belongs to the CREB family, may play important roles in inflammation, and can also function as a tumor suppressor via altering cellular stress in multiple tumors." (PMID 33390173, 2021). "Our study suggests that ATF3 plays an anti-tumor function in TSCCs through the negative regulation of its downstream targets, IFI6 and IFI27." (PMID 33539340, 2021). "Our data showed that chemotherapy, by itself, without any signals from a primary tumor is sufficient to make the lung a cancer-friendly environment in a host-Atf3-dependent manner." (PMID 34298975, 2021). "Consistent with previous reports in other tumor types, ATF3 expression was significantly lower in GC tissues than in normal tissues (p = 0.0076)." (PMID 34728784, 2021).
tumor (continued). "Thus, these xenograft models demonstrated that IFI6 promotes ESCC tumor growth in vivo, and again demonstrated a critical role of IFI6 in mitochondrial Ca2+, OXPHOS efficiency and ATF3/NOX4 axis." (PMID 32727517, 2020). "Similarly, ATF3 was induced in response to IGG and PB in the two human tumour cell lines tested while knockdown of ATF3 protected cells from both drugs." (PMID 33370278, 2020). "Higher ADORA1, lower ATF3, and lower PD-L1 expression levels were noted in tumor tissues from non-responders among anti-PD-1 antibody (nivolumab)-treated NSCLC patients." (PMID 32516941, 2020). "Therefore, identifying molecules that increase the expression of ATF3 and JDP2 can be used to control tumor growth and metastasis spread." (PMID 30670778, 2019). "In this study, however, ATF3 suppressed the in vitro migration and invasion of HCT116 β-catMut or β-cat WT cells, whereas ATF3 gene silencing did not significantly affect in vitro cell proliferation and in vivo tumor growth in xenograft assays." (PMID 29966001, 2018). "This included rapid induction of histone hyperacetylation, indicating effective and specific inhibition of HDACs, and the transcriptional induction of ATF3 and JUN expression, two well-established target genes of HDACi, which have been shown to be induced by HDACi across a range of tumour types." (PMID 30562958, 2018). "Overall, our data demonstrate that iNOS inhibition could impair EMT and tumor cell migration by impairing ER stress (IRE1α/XBP1) and the crosstalk between ATF4, ATF3, and TGFβ." (PMID 25849745, 2015). "Some of these gene nodes have been shown to be functionally involved in other cancer types, including regulation of tumor cell proliferation (Creb, C/ebp, ATF3, ATF4), invasion (MTHFD2, FGF2) and metastasis (PTGS1/COX1, E-selectin, ATF3, FGF2, IL1A, MMP1, MMP13)." (PMID 24124450, 2013). "To study the effects of pardaxin on tumor functions, we performed a real-time RT-PCR analysis of caspase-3, caspase-7, caspase-8, caspase-9, Bax, Bcl-2, STAT2, ATF3, STAT3, SOCS3, IL-2, cathelicidin, TNF-α, MyD88, NF-κB1, p65, IFN-β1, IFN-γ, IL-1β, IL-6, IL-7r, and IL-10." (PMID 23015777, 2012). "Moreover, Lu and co-workers elegantly demonstrated that ATF3 is capable of suppressing a Ras-mediated tumorigenicity of murine fibroblasts (ATF3-/- versus ATF3+/+ fibroblasts) in an in vitro, as well as in an in vivo model, hence supporting our hypothesis of a tumor suppressive role." (PMID 21129190, 2010). "Additionally we selected seven other genes, ATF3, ADAMTS1, EGFR, PRNP, IGFBP6, ID4 and FN1, found to be differentially expressed according to tumor subtype and ER+/ER- classification from the tumor-specific differentially expressed gene-set." (PMID 19116033, 2008). "A small fraction of large, apparently normal, ducts in both normal mammoplasty tissues and in tumor-adjacent normal tissue exhibited strong nuclear ATF3 expression in the basal layers (not shown)." (PMID 18808719, 2008). "Our observation of ATF-3 and NAG-1 induction by CDIM9 may also contribute to tumor growth inhibition." (PMID 17764562, 2007). "Additionally, ATF3 downregulates CH25H, a critical regulator of T cell trogocytosis and survival, in intra-tumoral cytotoxic T cells, resulting in their decreased viability and compromised anti-tumor immune responses." (PMID 41502516, 2025). "Surprisingly, acinar loss of ATF3 restricted neoplastic lesion progression more than global deletion, suggesting opposing roles for ATF3 in epithelial and non-epithelial compartments of PDAC tumours." (PMID 41198649, 2025). "Additionally, HIF-1α recruits TET1 to demethylate the ATF3 promoter, activating ATF3 transcription, which drives alternative splicing of P4HA1 to generate the P4HA1-9a isoform that promotes collagen deposition in the ECM and increases tumor cell invasiveness." (PMID 40813760, 2025).
tumor (continued). "Results showed that ATF3 knockdown reduced SLC7A7 expression, activated mTORC1 signaling, and upregulated lipogenesis-related enzymes, implying that downregulation of SLC7A7 may contribute to the enhanced tumor growth observed upon ATF3 knockdown." (PMID 39996726, 2025). "ATF3 (activating transcription factor 3) has conventionally been characterized in oncological research as a stress-inducible transcription factor that typically exerts a negative regulatory influence on the p38 MAPK pathway within cells, potentially suppressing tumor growth and invasion." (PMID 41294838, 2025). "Current evidence points towards the importance of tumor-initiating receptor-ligand interactions, e.g., FcγR-antibody complexes, TCR-MHC engagement, CD47-SIRPα signalling, cell intrinsic regulators such as CH25H mediated cholesterol metabolism and ATF3 transcriptional control within the TME." (PMID 41181711, 2025). "AETC also reduced tumor volume and weight in nude mice, upregulated ATF3, p-MOB1, and p-YAP (Ser397), actively regulated cleaved PARP, and caspase-9/8/3, showing its role in inducing apoptosis in NSCLC cells in vitro and in vivo through the ATF3-Hippo-YAP pathway." (PMID 38474640, 2024). "However, even in the absence of Atf3 expression in PSNs, the tumor can induce a significant transcriptional change in the tumor-innervating PSNs, leading to increased transcription of multiple genes, including some involved in nociceptor sensitization." (PMID 38433844, 2024). "Strikingly, treatment with metformin might reduce tumor growth, mainly by inducing the expression of a set of genes FOSB, EGR1, ZFP36, GPR183, ATF3, and NR4A1 which are involved in DNA-binding transcriptional activation, response to hormones and the Dcp1-Dcp2 mRNA-decapping complex." (PMID 39026155, 2024). "Inhibition of ATF3 expression caused by supplementation with doxycycline after cardiac remodeling had already occurred did not have any impact on tumor growth or metastasis, indicating that the enhanced tumor effect was due to cardiac remodeling and was independent of ATF3 expression." (PMID 38279150, 2024). "In addition, it was found that, among NSCLC patients treated with anti-PD-1 antibodies, lower ATF-3 and PD-L1 expression in tumor tissues from non-responder patients was shown." (PMID 36582540, 2022). "While the role of these transcription factors in a stress-inducible state likely differs from their role in untreated tumors, this result demonstrates that NACT-induced ATF3 and EGR1 may also have very different, unique roles within the tumor microenvironment in a post-NACT setting as well." (PMID 36131935, 2022). "Thus, fibroblasts lacking JDP2 and ATF3 expression, promote tumor growth and blood vessel perfusion." (PMID 30670778, 2019). "We asked whether each one of these components contributes to tumor growth in the absence of ATF3 and JDP2 expression." (PMID 30670778, 2019). "Since JDP2 and ATF3 may compensate for one another in the absence of their counterpart, we examined the effect of double deficiency of ATF3 and JDP2 (dKO) on tumor growth and metastasis." (PMID 30670778, 2019). "We therefore initially hypothesized that tumor metastasis will be significantly abrogated in mice lacking both ATF3 and JDP2, as both transcription factors compensate for the loss of each other." (PMID 30670778, 2019). "However, neither the knockdown nor overexpression of ATF3 in these cells had a significant effect on tumor growth." (PMID 29966001, 2018). "Thus, the function of ATF3 in tumor progression, including metastasis, has not yet been fully characterized." (PMID 28402947, 2017). "Interpretation of these results is complicated by the simultaneous expression of ATF3 at high levels in stromal components of these tumors, and by the fact that expression within the epithelial cell compartment is by no means universal within a given tumor." (PMID 18808719, 2008).
tumor (continued). "None of the tumors examined appeared to have strong nuclear ATF3 expression in all tumor cells." (PMID 18808719, 2008). "However, ATF3 is expressed in epithelial and non-epithelial cells of neoplastic lesions, and studies in other cancer models suggest cell-specific roles for ATF3 have opposing effects on tumour progression." (PMID 41198649, 2025). "Furthermore, in the present study, dendritic cells were not chronically exposed to the complex tumor microenvironment, which could also explain why ATF3 exhibited antitumor effects in our experimental setting." (PMID 41294838, 2025). "It was found that ATF3, and BIK were significantly overexpressed in tumor tissues, suggesting that these proteins may be involved in tumorigenesis and progression, particularly related to tumor cell proliferation, apoptosis inhibition, or microenvironment regulation." (PMID 40115255, 2025). "It was observed that three key FRGs (ALB, ATF3, and DUSP1), which were differentially expressed between renal tubular tissues with and without FSGS in patients receiving tumor nephrectomy, conformed to the predicted results." (PMID 38368317, 2024). "Furthermore, suppression of TSCC growth by ATF3 was verified in an in vivo mouse model, which also showed that ATF3 could promote TSCC cell differentiation, agreed to GO analysis result of RNA-seq data and the induction of differentiation has been considered to be an anti-tumor function of ATF3." (PMID 33539340, 2021). "Fibroblasts were the major stromal component responsible for the increased tumor growth, since co-implantation of cancer cells with MEFs lacking both ATF3 and JDP2 was able to mimic the tumor growth phenotype developed in dKO mice." (PMID 30670778, 2019). "In cervical DRGs (C3–C8), which innervated the tumor-bearing back skin, we did not see a significant reduction in the percentage of P2X3+ neurons after CTCL but observed significant increases in ATF3 colocalization with P2X3 on days 40 and 60 (P < 0.001)." (PMID 36520531, 2023). "Despite not detecting elevated ATF-3 expression or CD68+ macrophage density, MC38 tumor development led to significant mitochondrial dysfunction in the DRGs of tumor-bearing animals, by the third week after MC38 injection (n = 4 biological replicates/group in duplicates)." (PMID 35962398, 2022). "However, regarding ATF3-IR, there was no change in expression in MOC1 tumor-bearing male (p = 0.773) or female mice (p = 0.152) compared to PID40 sham." (PMID 36172037, 2022). "All tumor cells from the different groups expressed K14, however, we found a lower expression of K14 in TSCC cells induced by the high expression of ATF3, but not in cells with co-expression of ATF3 and IFI6 or IFI27." (PMID 33539340, 2021).